WFS1 (wolframin ER transmembrane glycoprotein)
Diseases named in the same sentence as WFS1 in open-access papers (continued):
Sharing a sentence is not in itself a finding about the gene and the disease.
tumor (4 papers, 2020 to 2025). "Stemness index analysis revealed that decreased WFS1 expression was associated with increased tumor grade and enhanced tumor stemness, suggesting increased malignancy of EC." (PMID 39478865, 2024). "Specifically, reduced WFS1 expression was found to be associated with increased tumor grade and enhanced tumor stemness, indicative of increased malignancy in patients with EC." (PMID 39478865, 2024). "The results suggested that, except for the G1 and G2 stages, significant differences were present in all other groups, with higher tumor grades being associated with lower WFS1 gene expression and increased risk levels." (PMID 39478865, 2024). "Furthermore, utilizing the TIMER database, we identified a strong correlation between WFS1 and immune cell infiltration within tumor tissues, which may contribute to the increased risk associated with decreased WFS1 expression." (PMID 39478865, 2024). "We categorized patients on the basis of tumor grade and analyzed WFS1 expression across different tumor grades." (PMID 39478865, 2024). "Collectively, these results underscore the influence of WFS1 expression on glycolytic processes in EC cells, thereby influencing tumor metabolic mechanisms." (PMID 39478865, 2024). "UALCAN analysis indicated that the transcription levels of GAD1, SPP1, and WFS1 were markedly higher in HCC tissues than in peri-tumor control tissues in the subgroup analyses." (PMID 34869039, 2021). "In addition, RT-qPCR analysis revealed that LOXL2 and SPTBN1 were predominantly expressed in normal cell lines, whereas higher levels of NCKAP1L, RUNX2, and WFS1 were detected in tumor cell lines." (PMID 41164190, 2025). "The WFS1 gene was expressed only in small amounts in monocytes, which are important immunomodulatory cells in the human body that influence tumor escape as well as tumor immunity." (PMID 39478865, 2024). "Given the predominant localization of Tcm_CD4 within secondary lymphoid organs, a decrease in Tcm_CD4 cell attributed to low WFS1 expression may contribute to an increased likelihood of tumor tissue metastasis to the lymph nodes." (PMID 39478865, 2024). "Furthermore, The degree of tumor differentiation was notably reduced in the subset characterized by low WFS1 expression." (PMID 39478865, 2024). "In addition, WFS1 expression was correlated with tumor microenvironment features such as immune cell infiltration." (PMID 39478865, 2024). "Moreover, we assessed the influence of WFS1 on tumor stemness by conducting tumor stemness index analysis on the basis of WFS1 expression grouping." (PMID 39478865, 2024). "The tumor samples were then ranked according to the median level of WFS1 expression." (PMID 34869039, 2021). "In addition, the WFS1 gene was hardly expressed in other immune cells in EC tumor tissues, which may be one of the reasons for the worse prognosis of EC patients in the WFS1 low-expression group." (PMID 39478865, 2024). "TIMER and GEPIA databases revealed that WFS1 was significantly positively correlated and EHHADH was negatively correlated with tumor immune cell infiltration and immune checkpoint expression." (PMID 34869039, 2021). "Taken together, these results suggested that WFS1 and EHHADH played a critical role in tumor immune escape, which was involved in the carcinogenesis of HCC." (PMID 34869039, 2021). "Compared with peri-tumor samples, GAD1, SPP1, and WFS1 were significantly upregulated in tumor tissues, and GOT2, EHHADH, and APOA1 were significantly downregulated in tumor tissues." (PMID 34869039, 2021). "Our findings suggested that WFS1 and EHHADH played essential roles in tumor growth by triggering immune checkpoints in HCC, and are thus promising prognostic biomarkers for patients receiving immunotherapy." (PMID 34869039, 2021).
tumor (continued). "GAD1, SPP1, and WFS1 were upregulated, whereas GOT2, EHHADH, and APOA1 were downregulated in HCC samples compared with peri-tumor controls, and this was consistent with the results in the ICGC, GSE14520, GSE54236, GSE107170, and GSE36376, validation datasets." (PMID 34869039, 2021). "Additionally, paired analyses were conducted on tumor tissues and adjacent nontumor tissues from the same patient, which revealed significant differences in WFS1 expression." (PMID 39478865, 2024).
myopathy (1 paper, 2021). A disease of the muscle in which the muscle fibers do not function properly. "Interestingly, skeletal muscle seems to be spared in WS with myopathy not being reported in patients with confirmed pathogenic WFS1 mutations." (PMID 34650143, 2021).
neurodevelopmental disorder (1 paper, 2024). A behavioral and cognitive disorder with onset during the developmental period that involves impaired or aberrant development of intellectual, motor, or social functions. "Clinically, she (IV-1) was suspected of having a neurodevelopmental disorder, while her genetics confirmed the same diagnosis via WES, identifying an ultra-rare, mono-allelic missense variant in the WFS1 gene." (PMID 39767643, 2024).
neurological disorders (1 paper, 2016). "Since alterations in WFS1 function seem to take place in different neurological disorders, our work may also have rather broad implications for understanding the role of mitochondrial dynamics in neuropsychiatric diseases." (PMID 27434582, 2016).
WFS1 also shares sentences with these, for which no sentence is quoted: diabetes insipidus (31 papers); Hearing impairment (17); Alstrom syndrome (4); psychosis (4); Usher syndrome (4); autism (3); Bardet-Biedl syndrome (3); peripheral neuropathy (3); Blindness (2); Crohn disease (2); development delay (2); diabetic ketoacidosis (2); Friedreich ataxia (2); metabolic disorders (2); metabolic syndrome (2); mitochondrial disease (2); retinal degeneration (2); ) channelopathies (1); Adult onset (1); Alport syndrome (1); Anosmia (1); Arts syndrome (1); autosomal dominant disease (1); autosomal recessive hearing loss (1); branchio-oto-renal syndrome (1); carcinosarcoma (1); cataract-41 (1); cerebellar ataxia (1); CHARGE syndrome (1); chronic fatigue syndrome (1).
A further 51 diseases each share a sentence with WFS1 in 1 paper.